LEP (leptin)
Diseases named in the same sentence as LEP in open-access papers (continued):
Sharing a sentence is not in itself a finding about the gene and the disease.
Obesity (continued). "Further studies will be necessary to determine whether increased methylation of CpG within the leptin promotor is present at earlier developmental time points and thus contributes to the development of obesity in the CAP mice." (PMID 28645299, 2017). "Thus, in this study, ET was able to correct alterations on metabolic and lipid profile induced by obesity, including, insulin resistance, and increased blood levels of insulin, leptin, and triglycerides." (PMID 29038363, 2017). "Leptin, which is increased in obesity, activates 17-hydroxylase in the ∆5 pathway." (PMID 28784626, 2017). "In the light of our in vivo data that obesity resulted in significant suppression of renal claudin-2 expression, contrasting the sharp increase in the intestinal epithelium, we examined if leptin and/or DCA exposure may have similar effects in vitro." (PMID 28698546, 2017). "However, this elevation in blood leptin concentrations occurs without an ensuing decrease in food intake, indicating the presence of leptin resistance among individuals who exhibit obesity." (PMID 28481261, 2017). "However, latest research have found that the central activation of PPARγ or arachidonic acid contributes to obesity by direct regulation of indigestive behaviors or impairment of hypothalamic leptin signaling and hepatic energy homeostasis." (PMID 28806763, 2017). "The lower levels of leptin found in patients with fibromyalgia and overweight/obesity in our study could be related to changes in the hypothalamic-pituitary-adrenal (HPA) axis." (PMID 28226002, 2017). "Some studies assessing HCC in human tissue have provided evidence that leptin could play a role in obesity-related tumorigenesis." (PMID 28758929, 2017). "This strain has antioxidant, hypoglycemic, and hypocholesterolemic properties in animal studies, thereby could be an interesting alternative for treating obesity, which is characterized by high leptin levels." (PMID 28348560, 2017). "Obesity may increase the risk for TNBC, which is, at least partially, ascribed to the influence of adipokine leptin." (PMID 28415788, 2017). "If leptin signaling in birds is truly different, it means that there is another way that vertebrates manipulate energy stores and thus potentially new avenues to pursue that will help us understand human obesity." (PMID 28443063, 2017). "Leptin is the main adipokine that is positively related to obesity." (PMID 28662701, 2017). "The obtained results seem to correspond with that described by other authors; the phenomenon of the plasma leptin concentration relationship with the level of obesity, the volume of body fat, insulin resistance, plasma concentration of triacylglycerols, and pro-inflammatory cytokines." (PMID 28758947, 2017). "Additionally, the association with menstruation disturbances was stronger for early onset obesity potentially due to the leptin levels which regulates the gonadotropin surge initiating pubertal stages." (PMID 28877677, 2017). "Besides leptin, other pro-inflammatory cytokines - Interleukin-6 (IL-6) and tumor necrosis factor (TNF) are linked strongly to obesity and have been found to have a role in development of CC." (PMID 28819564, 2017). "Furthermore, increased serum fatty acid levels and leptin are also proved to be capable of predicting poor prognosis of PCa patients with obesity." (PMID 29029491, 2017). "In addition, fish oil rich in n-3FA has been shown to increase the plasma level of adiponectin in rodents and in human subjects and to decrease plasma leptin concentrations thus reversing the protumorigenic adipokine profile induced by obesity." (PMID 29271901, 2017). "In addition, obesity was demonstrated to be accompanied by the decreased level of adiponectin and the increased expression of leptin and kisspeptin; therefore, there is a growing interest in these adipokines concerning obesity and pregnancy." (PMID 28409493, 2017).
Obesity (continued). "Leptin is known to contribute to the colon tumor development in genetic models of obesity." (PMID 28170448, 2017). "Supporting the role of obesity in MS pathophysiology, five week calorie restriction has been shown to significantly reduce inflammation and demyelination, correlated with increased serum adiponectin and reduced IL-6 and leptin in EAE mice." (PMID 28708082, 2017). "This scenario may be analogous to leptin treatment in obesity and insulin treatment in type 2 diabetes, in which endogenous hormone resistance may limit efficacy and result in side effects." (PMID 28694840, 2017). "Levels of leptin in humans increase with obesity and are higher in females than in males." (PMID 28278178, 2017). "Obesity is characterized by high levels of leptin and estrogen, which increases cancer growth." (PMID 28659656, 2017). "Adipokines such as leptin, adiponectin, resistin and PAI-1 are physiologically active cytokines secreted from adipocytes that play an important role in the pathogenesis of MS through inflammation associated with obesity, atherosclerosis and diabetes." (PMID 29258500, 2017). "Furthermore, DNA hypo-methylation in the promoter region of leptin gene was found to correlate to obesity in animals models." (PMID 28645299, 2017). "These INDELs and VNTRs could be found in the obesity loci or genes from the earliest GWAS and candidate gene association studies, like FTO, genes in the leptin–proopiomelanocortin pathway, and UCP2/3." (PMID 28615046, 2017). "In ob/ob mice, a murine model of obesity characterized by mutations in the gene responsible for the production of Leptin, the absence of PlGF significantly prevented weight gain." (PMID 28590409, 2017). "Therefore, we added recombinant mouse leptin protein to the medium to indirectly mimic the physiological conditions in obesity." (PMID 28182687, 2017). "While most adipokines are upregulated in obesity and promote inflammatory responses (e.g., Leptin, TNFα, IL-6, and IL-18), others may act as anti-inflammatory modulators (e.g., adiponectin, and secreted frizzled related protein 5)." (PMID 28758929, 2017). "The majority of studies have investigated leptin in females in relation to diabetes and obesity." (PMID 28348585, 2017). "As these receptors are blocked by the PTDs, they may become insensitive (for example, leptin resistance), inducing hypermetric hormonal responses with resultant obesity and metabolic dysregulation." (PMID 28243210, 2017). "According to the literature, leptin levels may be increased in patients with fibromyalgia and overweight/obesity, since leptin is considered a pro-nociceptive adipokine." (PMID 28226002, 2017). "In addition, the observed developed obesity in male MT3-null mice is due likely to abnormal leptin signaling in the hypothalamus." (PMID 28538697, 2017). "Leptin is involved in the regulation of food intake; therefore, leptin insensitivity may lead to obesity." (PMID 28708880, 2017). "For example, a molecular mechanism of tumorigenesis in obesity has been proposed, involving secretion of adipokines (leptin, adiponectin and increased inflammatory cytokines) and secondary effects of obesity that increase anabolic pathways, such as insulin-insulin growth factor (IGF) signaling." (PMID 28580187, 2017). "Transcript levels of PGC-1α have been reported to be markedly lower in mouse models of muscle atrophy induced by obesity, diabetes, or denervation, whereas energy restriction or leptin administration enhances skeletal muscle PGC-1α expression in rodents and humans." (PMID 28054981, 2017). "We observed that “more inflammatory” strains produced more leptin as well as increased Ob-Rb receptor expression on macrophages, which is according to the notion of pro-inflammatory property of leptin and its adverse role in obesity." (PMID 28348560, 2017).
Obesity (continued). "As such, adipokines including adiponectin and leptin represent key players in obesity-related disorders and might be involved in the pathogenesis of NAFLD and HCC." (PMID 28758929, 2017). "Thus, our study has revealed the mechanistic link between leptin, autophagy and ER stress, providing novel insights into the pharmacologically therapeutic target for obesity and inflammation." (PMID 29250056, 2017). "Obesity in the elderly is also related to changes the hormonal environment, which includes a decline of growth hormone and testosterone, decreased responsiveness to thyroid hormone and leptin, and increased prolactin and cortisol levels." (PMID 29244825, 2017). "Antipsychotics can increase rates of obesity, with consequent upregulation of IL-6, and leptin." (PMID 29163240, 2017). "Thus, SR3306-mediated JNK inhibition enhances STAT3 as well as PI-3K signaling pathways, contributing to the amelioration of leptin resistance and obesity in the DIO mice." (PMID 28165482, 2017). "Deletion of MC3R and/or MC4R results in leptin resistance and obesity." (PMID 28270795, 2017). "Although it was statistically significant (OR = 1.04), among nonobese women, the association between leptin levels and knee OA was less which further indicated that leptin levels were strongly associated with obesity-related OA." (PMID 28250578, 2017). "Therefore, leptin was used as an activator in the present study to investigate the physiological conditions in obesity." (PMID 28182687, 2017). "In addition to leptin resistance, hyperinsulinemia also contributes to the obesity phenotype in these mice, at least in part, by inducing hypothalamic FASN level and activity, which in turn, causes hyperphagia and lower physical activity." (PMID 28184213, 2017). "Central mechanisms may be relevant in obesity-related hypertension and include activation of leptin and POMC pathway, and obstructive sleep apnea syndrome, with activation of chemoreceptor-mediated reflexes related to intermittent hypoxia." (PMID 28966594, 2017). "Adiponectin, leptin, and resistin are adipocytokines that are related to obesity." (PMID 28246535, 2017). "There might be a potential interaction between them and according to some evidence amylin agonism could even restore leptin responsiveness in diet-induced obesity." (PMID 28369078, 2017). "Importantly, we show here that circulating survivin levels are increased in obesity, and are positively correlated with circulating leptin." (PMID 28518147, 2017). "However, in obesity, elevated levels of the hormone fail to regulate the body weight due to leptin resistance." (PMID 29142618, 2017). "On the other hand, mice with a POMC-specific deletion of MFN2 (mitofusin 2), a key protein for mitochondrial fusion and the formation of ER–mitochondria contacts, display a loss of these interactions, defective POMC processing, ER stress-induced leptin resistance, and obesity." (PMID 28270795, 2017). "Leptin-responsive pericytes evaluate energy availability to inform tissue construction by modulating Hedgehog pathway activity and thus, are at the root of progressive obesity-related tissue pathology." (PMID 28427343, 2017). "Since the levels of this adipokine in circulation are a direct function of body fat mass, individuals with developed obesity typically show chronic hyperleptinemia, which, in time, could lead to the development of central and/or peripheral leptin resistance." (PMID 28959235, 2017). "Obesity leads to high circulating concentrations of insulin, leptin and insulin-like growth factor-I (IGF-I) and low levels of adiponectin, which have been described to promote prostate cancer growth and progression, thus increasing the risk of advanced prostate cancer." (PMID 29228634, 2017). "As the expansion of adipose tissue in obesity is accompanied by the augmentation of leptin, we hypothesized that leptin may play a key role in H4ac status in PBMC of the obese." (PMID 29142617, 2017).
Obesity (continued). "Leptin is one of the major adipokines in obesity that indicates the severity of fat accumulation." (PMID 28809927, 2017). "Butyrate-induced increased levels of leptin may be important in preventing obesity, as leptin acts within the hypothalamus to reduce food consumption and increase energy expenditure." (PMID 29231905, 2017). "However, most patients with bioinactive leptin are presently likely to remain undiagnosed as so far, only the immunoassay detecting total immunoreactive leptin is used as part of the recommended work-up of severe early-onset obesity." (PMID 28007844, 2017). "In summary, our study identified an importance for VMAT2-mediated neurotransmission in mediating hedonic feeding and binge-like eating behavior, providing novel insight on the interactive roles of leptin and DA, two of the most extensively studied brain systems, in obesity development." (PMID 28560316, 2017). "We found that EMD mice exhibit mild obesity as a result of hyperphagia, increased adiposity, elevated leptin and insulin plasma concentration, hypertriglyceridemia, impaired glucose tolerance, and decreased hypothalamic leptin signaling." (PMID 28143489, 2017). "Therefore, further evaluation of the role of leptin in appropriately designed biological experiments is necessary, particularly when obesity and obesity-related infertility are growing problems in both human and animal populations." (PMID 28959235, 2017). "Furthermore, this IL-6 inflammatory response, mediated by chondrocyte-synovial fibroblast cross-talk, was enhanced by the obesity-related adipokine leptin." (PMID 28615667, 2017). "It is possible that normal vitamin D metabolism may be disrupted in obesity due to elevated levels of serum leptin, which has been shown to suppress the conversion of 25(OH)D to 1,25(OH)2D3." (PMID 28241878, 2017). "Obesity and T2DM are associated with increased plasma leptin levels, which fail to correct hyperglycemia in these patients because of the presence of leptin resistance, and these elevated plasma leptin levels are associated with IR, independent of obesity and insulin sensitivity." (PMID 28587203, 2017). "One possible mechanism by which obesity may lead to cognitive deficits is via alterations in circulating leptin." (PMID 28093279, 2017). "In conclusion, phyllodulcin is a potential sweetener that could be used to combat obesity by regulating levels of leptin, fat browning-related genes, and hypothalamic BDNF-TrkB signaling." (PMID 28934139, 2017). "The proarteriogenic process is also supported by increased VEGFR 2 expression in the tumor vessels under obesity conditions, which may result from increased leptin expression due to DIO." (PMID 28186980, 2017). "Increased maternal blood concentrations of leptin and decreased adiponectin levels, which are common disturbances in obesity, may be involved in offspring adiposity by programming fetal adipose tissue development." (PMID 28241462, 2017). "Thus, in the Iberian breed high levels of leptin fail to reduce appetite, fitting with a pattern of obesity by leptin resistance." (PMID 29271889, 2017). "Leptin can induce oxidative stress mediating a pro-inflammatory state and is a marker for obesity." (PMID 28185008, 2017). "Leptin and adiponectin, as two major adipokines derived from adipose tissue, have a broad spectrum of functions in the regulation of metabolism and are important link between obesity and MS." (PMID 29020116, 2017). "COH women present abnormalities in non-standard markers of cardiometabolic risk (sRAGE, leptin, high sensitive C-reactive protein), supporting the view that there is no healthy pattern of obesity." (PMID 28409494, 2017). "In addition, insulin and leptin levels were significantly affected by obesity and exercise training (Ob > C and Ob > ObET, respectively, P < 0.05)." (PMID 29038363, 2017). "Notably, the obesity induced by the disruption of leptin signaling resembles that observed following Pomc or Mc4r nullification." (PMID 28690493, 2017).
Obesity (continued). "It has been suggested that leptin actions may control obesity by modulating food intake, inhibiting adipogenesis, and triggering lipolysis." (PMID 28469684, 2017). "Next, the Ankrd26 gene expression was assessed in vitro by exposing 3T3-L1 adipocytes to either palmitate or oleate, representing saturated and unsaturated fatty acid species, which are abundant in the HFD, or alternatively to leptin, whose levels raise through obesity development." (PMID 28266632, 2017). "In addition to enhanced leptin secretion, obesity increases the recruitment of inflammatory macrophages into mammary adipose tissue." (PMID 29187227, 2017). "Obesity may cause chronic, low-grade systemic inflammation through increased levels of TNF-α, IL-6, leptin, free fatty acids, and TLR4 and decreased adiponectin levels." (PMID 29049401, 2017). "In obesity, adipocytes secrete more leptin and less adiponectin, leading to the hypothesis that leptin/adiponectin ratios are useful biomarkers of adipocyte hypertrophy, insulin resistance, and cardiovascular risk." (PMID 28626772, 2017). "As product of obesity gene from adipocytes, leptin is defined as potent angiogenic factor involving in tumorigenesis, angiogenesis and metastasis, and the expression of leptin receptor (ObR) in malignant carcinoma was confirmed to be corresponded with tumor neoangiogenesis significantly." (PMID 28938545, 2017). "This 50 kDa adipokine was first discovered in a rat model when identifying genes that were differentially expressed during the development of obesity and type 2 diabetes; vaspin level is low in obesity and suppresses leptin, TNF-α, ICAM, and resistin synthesis." (PMID 28490838, 2017). "It has been reported that leptin, an obesity-related factor, upregulates MMP-2 and induces EMT." (PMID 28505114, 2017). "It is reported that leptin levels increase with obesity and correlate significantly with body fat percentage and that the association with CVD may be partly influenced by genetic factors." (PMID 28278178, 2017). "In addition, other hormonal factors including insulin resistance, adipocytokines, AMP-activated protein kinase and leptin, which are related to obesity, are also important factors for the formation and development of breast cancer." (PMID 29216920, 2017). "As adipose tissue increases in obesity, the quantities of anti-inflammatory adipokines are reduced and the quantities of proinflammatory adipokines with oncogenic capability, such as resistin, leptin, visfatin, and chemerin, are augmented." (PMID 29089667, 2017). "So what is clear is that while the brain leptin–melanocortin pathway is central to mammalian food intake control with genetic disruption resulting in extreme obesity, subtle variations in these same genes influence an individual’s position in the normal distribution of BMI." (PMID 28013339, 2017). "Also, obesity is known to induce leptin resistance, leading to even higher circulating levels of leptin and further contributing to the pathogenesis of obesity-associated neurodegenerative diseases." (PMID 28154473, 2017). "In addition, adipokines, including leptin and adiponectin, are shown to be involved in linking depression to obesity." (PMID 29176959, 2017). "However, there is evidence that animals lacking melatonin still suffer LAN-induced metabolic alterations and loss of weight homeostasis, and the link of melatonin with leptin in human obesity is still inconsistent." (PMID 29097992, 2017). "However, obesity is characterized by hypothalamic unresponsiveness to leptin signals, which is known as leptin resistance." (PMID 28659656, 2017). "Other aspects related to leptin have been assessed in the pathophysiology of obesity." (PMID 27598976, 2017). "However, several other relevant pathways for lactation were also enriched such as STAT3 pathway, leptin signalling in obesity and NF-κB signalling." (PMID 28317898, 2017).